BTG4 (BTG anti-proliferation factor 4)
Description:
Adapter protein that bridges CNOT7, a catalytic subunit of the CCR4-NOT complex, to EIF4E (By similarity). Facilitates maternal mRNAs decay during the maturation of oocytes and in the fertilized egg, and is required for the maternal-zygotic transition (MZT), zygotic cleavage and initiation of embryonic development.
Synonyms: PC3B; APRO3; OOMD8; OZEMA8
Tractability: No criterion of Open Targets' tractability assessment is met for any kind of drug.
Gene: Protein-coding gene on chromosome 11 (111,467,526 to 111,514,367, reverse strand). Ensembl gene ENSG00000137707.
Subcellular location (Human Protein Atlas): Endoplasmic reticulum; Golgi apparatus
Pathways (Reactome):
Developmental Biology: M-decay: degradation of maternal mRNAs by maternally stored factors
Gene Ontology:
Molecular function: protein binding
Biological process: negative regulation of cell population proliferation; neuron differentiation; regulation of cell cycle
Cellular component: cytoplasm; nucleus
Genetic constraint (gnomAD): Loss-of-function variants: 13 observed, 19.28 expected, observed/expected ratio (o/e) 0.67, 90% interval 0.44 to 1.07. The upper end of that interval is the gene's LOEUF score, 1.07, which puts it in group 4 of 6, group 1 being the genes least tolerant of losing a copy. Missense variants: 224 observed, 263.26 expected, observed/expected ratio (o/e) 0.85, 90% interval 0.76 to 0.95. Synonymous variants: 84 observed, 88.16 expected, observed/expected ratio (o/e) 0.95, 90% interval 0.8 to 1.14.
Homologues: Orthologues: chimpanzee BTG4 (99% identical), macaque BTG4 (97% identical), pig BTG4 (83% identical), dog BTG4 (82% identical), mouse Btg4 (73% identical), guinea pig BTG4 (72% identical), rat Btg4 (72% identical), tropical clawed frog btg4 (57% identical), zebrafish btg4 (51% identical). Paralogues in human: BTG3 (45% identical), BTG1 (22% identical), BTG2 (21% identical).
Diseases named in the same sentence as BTG4 in open-access papers:
BTG4 is named in the same sentence as 18 diseases in open-access papers, as found by Europe PMC text mining. Sharing a sentence is not in itself a finding about the gene and the disease. The quoted sentences say what the papers report.
colon cancer (4 papers, 2017 to 2025). "BTG4 mRNA was significantly decreased in both lung and colon cancer samples compared with their normal counterpart tissues." (PMID 32093041, 2020). "There were few datasets for BTG4 in our analyses, but it was proposed interestingly by others that inactivation of BTG4 may be a contributory factor for colon cancer." (PMID 28922388, 2017). "Our data also found that the expression of BTG4 is downregulated in lung and colon cancers, and overexpression of BTG4 can inhibit proliferation and migration, and induce apoptosis, suggesting that similar to BTG2 and BTG3, BTG4 might also act as a potential tumor suppressor." (PMID 32093041, 2020). "The demethylation effect was further supported by the reactivation of several genes silenced by DNA methylation in colon cancer cells, such as MGMT, carbohydrate sulfotransferase 10 (CHST10), and B-cell translocation gene 4 (BTG4), leading to inhibited cancer cell growth." (PMID 41226811, 2025).
Infertility (4 papers, 2016 to 2024). "Homozygous mutations in BTG4 caused zygotic cleavage failure in 4 independent affected females with infertility of unknown cause." (PMID 38606321, 2024). "Meanwhile, in another study we have identified infertile women carrying BTG4 mutations." (PMID 33004802, 2020). "These properties make Btg4 a good candidate whose mutation could contribute to the spontaneous abortive activation of eggs that has been implicated in infertility in humans." (PMID 27605379, 2016). "The identification of BTG4 mutations in infertile women supports our hypothesis that BTG4/CCR4-NOT-induced mRNA deadenylation is involved in the regulation of maternal mRNA stability during human MZT." (PMID 33004802, 2020).
breast carcinoma (2 papers, 2017 to 2023). "In survival analyses based on Kaplan-Meier Plotter, TOB1, BTG1 and BTG4 showed significant associations with survival outcome of different subtypes of breast cancer." (PMID 28922388, 2017).
colorectal cancer (2 papers, 2017 to 2020). A primary or metastatic malignant neoplasm that affects the colon or rectum. "Three studies also suggested that BTG4 is downregulated in gastric cancer, chronic lymphocytic leukemia, and colorectal cancer." (PMID 32093041, 2020). "In addition, BTG4 is downregulated in lung and colorectal cancers, and overexpression of BTG4 inhibits cell growth and induces apoptosis in cancer cells." (PMID 32093041, 2020). "BTG4 was related to survival outcomes in breast and colorectal cancer." (PMID 28922388, 2017). "Only lower expression of BTG4 revealed poor prognosis in colorectal cancer patients." (PMID 28922388, 2017). "TOB2, BTG2 and BTG4 had no expression difference between colorectal cancer and normal tissues." (PMID 28922388, 2017).
female infertility (2 papers, 2016 to 2023). Diminished or absent ability of a female to achieve conception. "Impediment in maternal RNA clearance by genetic inactivation of the RNA degradation-associated genes Btg4, Pabpn1l, or Cnot6l leads to MZT failure and female infertility in mice." (PMID 37025171, 2023). "Our findings reveal a major role of Btg4 in the formation of a viable egg and suggest that the impaired embryonic development and female infertility observed in Btg4−/− mice originate at least partially from defects during meiosis." (PMID 27605379, 2016). "Embryos with either BTG4 or PABPN1L depletion will be arrested at the 1∼2-cell stage and characterized by female infertility." (PMID 37025171, 2023).
gastric cancer (2 papers, 2020 to 2023). A primary or metastatic malignant neoplasm involving the stomach. "Studies have suggested that BTG4 is critical for the degradation of maternal mRNAs in mice during the process of maternal-to-zygotic transition, and downregulated in cancers, such as gastric cancer." (PMID 32093041, 2020).
lung carcinoma (2 papers, 2017 to 2020). "Of note, in lung cancer tissues, the expression levels of BTG4 mRNA were significantly associated with the clinical stage." (PMID 32093041, 2020).
clear cell renal cell carcinoma (1 paper, 2017). "As for clear cell renal cell carcinoma, which account for the majority of kidney cancer, BTG2 and BTG4 were reduced, while BTG1 was elevated in clear cell renal cell carcinoma compared with normal kidney tissue group." (PMID 28922388, 2017).
melanoma (1 paper, 2017). A malignant, usually aggressive tumor composed of atypical, neoplastic melanocytes. "CHST10 is also known to inhibit the invasiveness of melanoma cells, and BTG4 has anti-proliferative properties." (PMID 28241740, 2017).
ovarian carcinoma (1 paper, 2022). A malignant neoplasm originating from the surface ovarian epithelium. "While the expression of NOG, S1PR1, BTG4, and CREB5 genes was significantly increased, that of RASSF9, DNMT1, BST2, and SETD1A genes was significantly decreased in CFP1-deleted A2780 and ES-2 ovarian cancer cells, based on qRT-PCR results." (PMID 35864225, 2022).
cancer (9 papers, 2012 to 2025). A tumor composed of atypical neoplastic, often pleomorphic cells that invade other tissues. "In the present study, we comprehensively analyzed the role of TOB1, TOB2, BTG1, BTG2, BTG3 and BTG4 in cancer from the perspective of bioinformatics." (PMID 38062199, 2023). "Through a series of bioinformatics analysis, the findings in our study supported the important role of TOB1, TOB2, BTG1, BTG2, BTG3 and BTG4 in pan-cancer and provided a reliable basis for detecting biomarkers of cancer." (PMID 38062199, 2023). "We used bioinformatics methods to analyze the characteristics of TOB1, TOB2, BTG1, BTG2, BTG3 and BTG4 in pan-cancer." (PMID 38062199, 2023). "Others were either showed to have a cancer-specific co-transcription pattern, such as miR-34/BTG4, or had independent transcription, such as miR-3188/JUND." (PMID 34572448, 2021). "BTG4, which was commonly low expressed in cancer and normal tissues, also could predict unfavorable prognosis for KICH, KIRC, LGG, LIHC, MESO and THCA with big HR values, indicating its significance in disease prognosis." (PMID 38062199, 2023). "Overexpression of BTG4 inhibits cell growth and induces apoptosis in cancer cells." (PMID 32093041, 2020). "However, the regulatory mechanism of BTG4 and its function in cancers remain elusive." (PMID 32093041, 2020). "We then determined whether BTG4 could affect cancer cell proliferation, migration, and apoptosis." (PMID 32093041, 2020). "Finally, we examined whether the expression of BTG4 is aberrantly changed in cancer tissues." (PMID 32093041, 2020). "Many BTG proteins such as BTG4, TOB1, TOB2 are aberrantly expressed and serve as negative regulators in tumorigenesis in various cancers." (PMID 24147003, 2013).
tumor (4 papers, 2020 to 2023). "StromalScore and ImmunoScore were used to analyze the correlation between APRO (TOB1, TOB2, BTG1, BTG2, BTG3 and BTG4) expression and tumor purity and tumor microenvironment characteristics." (PMID 38062199, 2023). "BTG4 and RERG genes implicated in tumor growth repression were found to be the most strongly up-regulated genes by anti-apoA-1 IgGs." (PMID 33245719, 2020). "BTG4 has antiproliferative properties and is a novel tumor suppressor." (PMID 32499821, 2020). "However, the expression levels of BTG4 in tumor was basically low." (PMID 38062199, 2023).
BTG4 also shares sentences with these, for which no sentence is quoted: atherosclerosis (1 paper); Cardiovascular Diseases (1); glioma (1); gynecological cancers (1); infection (1); kidney cancer (1).